RBP4 (retinol binding protein 4)
Diseases named in the same sentence as RBP4 in open-access papers (continued):
Sharing a sentence is not in itself a finding about the gene and the disease.
inflammation (8 papers, 2018 to 2022). Aberrant reaction of the microcirculation characterized by movement of fluid and leukocytes from the blood into extravascular tissues. "The detection of retinol-binding protein 4 and vitamin D-binding proteins in the urine is a consequence of tubulo-interstitial inflammation and injury of the tubular epithelium secondary to glomerular proteinuria." (PMID 36293475, 2022). "In the functional study, exogenous RBP4 attenuated the severity of IL-17A-induced neutrophilic airway inflammation." (PMID 35095906, 2021). "RBP4 protein is reported to induce endothelial inflammation through the stimulation of expression of proinflammatory molecules involved in leukocyte recruitment and adherence to the endothelium, including V-CAM-1, I-CAM-1, and E-selectin." (PMID 32156052, 2020). "RBP4 regulates macrophage foam cell formation and enhances chronic endothelial inflammation through the activation of macrophages, mediated through the c-Jun-N-terminal protein kinase (JNK) and Toll-like receptor 4 (TLR-4) pathways, along with the activation of NADPH oxidase and NF-Κb." (PMID 34758835, 2021). "Because RBP4 concentrations were positively related to oxidative stress markers, RBP4 may have a role in the initiation of endothelial inflammation." (PMID 30038059, 2018).
kidney (5 papers, 2017 to 2025). "Our data suggest retinol-binding protein (RBP4), beta-2-microglobulin (B2M), cystatin-C (CST3), hepcidin (HAMP), and fatty acid-binding protein (L-FABP) hold promise as candidates for kidney damage surveillance in Bothrops envenoming." (PMID 38536893, 2024).
heart disease (3 papers, 2014 to 2024). "However, following adjustment of the data for other CHD risk factors, the positive correlation between the RBP4 level and the risk of heart disease proved not to be statistically significant, thereby suggesting that RBP4 may not be a robust predictor of CHD." (PMID 24604418, 2014).
neurodegenerative disease (3 papers, 2020 to 2024). A disorder of the central nervous system characterized by gradual and progressive loss of neural tissue and neurologic function. "Increase in concentration of RBP4 induces neurodegenerative diseases." (PMID 32864980, 2020). "With no potential neurodegenerative disease link target, 18alpha-glycyrrhetinic acid can be considered the most potent and specific drug candidate against CST, while in the case of β-carotene, transthyretin and RBP4 may act as cross-targets in the brain." (PMID 39450315, 2024).
neurological disease (2 papers, 2022 to 2023). "Previous proteomics studies also reported a decrease in the abundance of Rbp4 in the CSF of patients with MS when compared with the clinically isolated syndrome, and with other neurological disorders (not validated)." (PMID 35135578, 2022).
bacterial infections (1 paper, 2026). "RBP4 may regulate pathological processes during bacterial infections." (PMID 41477556, 2026).
respiratory disorders (1 paper, 2023). "They studied 13 newborn infants with respiratory disorders and reported a significant increase in plasma retinol and RBP4 during and 14 days after dexamethasone exposure." (PMID 36678312, 2023).
RBP4 also shares sentences with these, for which no sentence is quoted: fetal growth restriction (4 papers); chronic hepatitis C (3); colon adenocarcinoma (3); End Stage Renal Disease (3); head and neck cancer (3); ocular coloboma (3); ovarian diseases (3); retinopathy (3); Anophthalmia (2); Arthritis (2); cerebrovascular disease (2); chronic heart failure (2); colitis (2); colon (2); dementia (2); essential hypertension (2); glomerulonephritis (2); glucose metabolism disorder (2); hepatitis C (2); Hypoglycemia (2); Osteopenia (2); Ovarian cyst (2); acute graft versus host disease (1); age-related macular degeneration (1); AIDS (1); alcoholic cirrhosis (1); alcoholic fatty liver disease (1); alcoholic liver diseases (1); allergic asthma (1); amyotrophic lateral sclerosis (1).
A further 75 diseases each share a sentence with RBP4 in 1 paper.